PTCH1 (patched 1)
Diseases named in the same sentence as PTCH1 in open-access papers (continued):
Sharing a sentence is not in itself a finding about the gene and the disease.
pancreatic cancer (23 papers, 2011 to 2024). "Hh ligand expression was shown to be restricted to epithelial carcinoma cells, whereas increased expressions of the Patched-1 (PTCH1) receptor and Gli1, a downstream mediator of Smo signalling, were detected in the tumour-associated stroma of mouse pancreatic tumour models." (PMID 24216702, 2013). "α-Ptch1 is a novel anti-PTCH1 antibody which reportedly reduced proliferation of pancreatic cancer cells; however, the data on this antibody is limited." (PMID 38612911, 2024). "Taken together, these data indicated that knockdown of IGFBP-2 inhibits EMT in pancreatic cancer cells, at least in part, through the Hedgehog pathway by suppressing PTCH1." (PMID 28977895, 2017). "Gedunin treated pancreatic cancer cells were effectively downregulated PTCH1, PTCH2, Gli1, SUFU and Shh proteins involved in Hedgehog/Gli signaling pathway." (PMID 26988754, 2017). "Silencing IGFBP-2 inhibited invasion and metastatic properties, partially through inhibiting PTCH1 in pancreatic cancer." (PMID 28977895, 2017). "Earlier it was reported that pancreatic cancer tissue had higher expression of Shh, PTCH1 and Gli 1 mRNA compared to adjacent normal pancreatic tissue." (PMID 26988754, 2017). "But another study reported that miR-212 promoted pancreatic cancer cell proliferation by inhibiting patched-1 in pancreatic cancer." (PMID 25965836, 2015). "The data demonstrate that the components of SHH signaling pathway, including the ligand (Shh), the signaling molecules (Patched-1, Patched-2 and Smoothened) and effectors (Gli1, and Gli2) are expressed in human pancreatic cancer cell lines and pancreatic CSCs." (PMID 22087285, 2011). "However, study of pancreatic cancer cells found that miR-212 promoted cell proliferation by targeting patched-1." (PMID 29190902, 2017). "The components of Sonic Hh signaling pathway, including the ligand (SHh), the signaling molecules (Patched-1, Patched-2 and Smoothened) and effectors (Gli1, and Gli2) are aberrantly expressed in human pancreatic cancer cell lines and pancreatic cancer stem cells." (PMID 26369833, 2015). "Of particular interest, Smoothened-dependent GDC-0449 treatment of pancreatic CSCs markedly inhibited expressions of SHH receptors (Patched-1, Patched-2 and Smoothened) and effectors (Gli1 and Gli2), thereby showing potential for therapeutic application for treatment of pancreatic cancer." (PMID 22087285, 2011). "PTCH-1 is found contribute to the function of IGFBP-2 in suppressing metastasis and EMT of pancreatic cancer." (PMID 28977895, 2017). "Another study demonstrates that Hh signaling activation is a very common event in pancreatic cancer, evidenced by the expression of PTCH1 and GLI1 in seven available pancreatic cancer cell lines and 54 pancreatic cancer surgical specimens." (PMID 23786654, 2013). "In case of pancreatic cancer, we found the expression of IHH, PTCH1 and SMO in pancreatic cancer cell line, which signified their role of hedgehog pathway activation in this type of cancer formation." (PMID 23935937, 2013). "PTCH1 directly inhibits smoothened (SMO) and in a mouse model of pancreatic cancer, SMO inhibition may facilitate chemotherapy delivery and extend survival by depleting tumor-associated stromal tissue." (PMID 31817155, 2019). "As a result, perturbation of SMO or PTCH1/PTCH2 receptors was not effective to reduce the activation of GLI1/GLI2/GLI3_A in pancreatic cancer model." (PMID 23935937, 2013). "Malignancies where PTCH1 is wild type—such as in GBM, pancreatic cancer, ovarian cancers etc.—the resultant effect of ligand-driven aberrant activation of Hh-pathway might be “dampened” or “mellowed down” by PTCH1-mediated negative feed-back mechanisms." (PMID 25775002, 2015).
pancreatic cancer (continued). "However, these factors are not related to the Wnt-independency phenotype in RNF43-mutant pancreatic cancer, since sgRNAs targeting KDM6A or negative regulators of GLI2 or YAP1, i.e., PTCH1, LATS1, and SAV1, were not enriched in ETC-159 versus vehicle-treated tumors in our initial CRISPR screens." (PMID 35536676, 2022).
melanoma (22 papers, 2013 to 2026). A malignant, usually aggressive tumor composed of atypical, neoplastic melanocytes. "TRIP4, which is associated with malignant melanoma, was repressed by PTCH1 but to a lesser extent than PTCH1/FLNB double knockdown, perhaps reflecting the more aggressive nature of mBCC." (PMID 41373535, 2025). "Thus, we cannot exclude that the increase in cholesterol accumulation caused by the inhibition of Ptch1 cholesterol efflux by sPAH also contributes to toxicity in melanoma cells." (PMID 32526884, 2020). "We have identified a small molecule produced by a marine sponge as being able to inhibit PTCH1 efflux activity and increase the efficacy of vemurafenib treatment on BRAF-mutated melanoma cells in vitro and in vivo in mice." (PMID 42001685, 2026). "Our results provide an additional proof that Ptch1 drug efflux inhibition increases the effectiveness of anti-cancer treatments and overcomes resistance of melanoma cells expressing Ptch1." (PMID 33810240, 2021). "We show that methiothepin enhances the efficacy of doxorubicin against melanoma cells by binding Ptch1 and inhibiting Ptch1 efflux activity." (PMID 33810240, 2021). "To this end, we evaluated the effect of MAPK7 silencing on HH-GLI-dependent proliferation induced by PTCH1 silencing in melanoma cells." (PMID 34681917, 2021). "In contrast, expression of Shh pathway components (Gli-1, Gli-2, and Ptch-1) in the nevi from P4 and P5 and melanoma markers (c-kit, MAGE, and CDK4) in the nevus from P1 was markedly increased." (PMID 33509032, 2021). "We recently reported that the Hedgehog receptor Ptch1 is strongly expressed in metastatic samples from a cohort of melanoma patients, and that a high expression level of Ptch1 in patient samples significantly correlated with a lower overall survival time." (PMID 33810240, 2021). "Here, we show that methiothepin also inhibits doxorubicin efflux and increases doxorubicin cytotoxicity in melanoma cells which endogenously overexpress Ptch1." (PMID 33810240, 2021). "We have demonstrated that Ptch1 pumps chemotherapeutic agents such as doxorubicin (dxr) which isused to treat many cancers, out of cancer cells that were derived from melanoma and adrenocortical carcinoma (ACC), thereby conferring resistance to chemotherapy." (PMID 33810240, 2021). "We conclude that sPAH is a very promising lead for vemurafenib resistant BRAFV600E melanoma where Ptch1 is overexpressed." (PMID 32526884, 2020). "We showed that PAH enhances the efficacy of vemurafenib against BRAFV600E melanoma cells, in vitro and in vivo, by directly interacting with Ptch1 and inhibiting vemurafenib efflux." (PMID 32526884, 2020). "The distribution of PTCH1 gene expression level for all TCGA patients compared to genes known to be well expressed in melanoma (GAPDH, ACTB, MITF) indicates that PTCH1 is well expressed in primary and metastatic samples." (PMID 32526884, 2020). "Western blots were performed on extracts from four melanoma cell lines that are sensitive or resistant to chemotherapy, and strong expression of Ptch1 was found in all of the studied cell lines." (PMID 32526884, 2020). "Remarkably, we observed that astemizole also inhibits dxr efflux from melanoma cells such as MeWo which endogenously express Ptch1, and increases dxr cytotoxicity in these cells (Sup." (PMID 32751066, 2020). "We also observed that sPAH was able to increase the cytotoxicity of cisplatin, another chemotherapeutic agent that we previously identified as a substrate of Ptch1, against melanoma cells in vitro." (PMID 32526884, 2020). "Decreased Ptch1 protein levels also increased doxorubicin accumulation in melanoma and leukemia cell lines known to aberrantly express Hh signaling components." (PMID 30110910, 2018). "This molecule (panicein A hydroquinone) was shown to inhibit doxorubicin efflux and to increase doxorubicin cytotoxicity in vitro, in human melanoma cells that endogenously over-express Ptch1." (PMID 30110910, 2018).
melanoma (continued). "The expression of Patched 1, here referred as Patched, is induced upon activation of the Hh pathway in several cancers: lung, breast, basal cells of the skin, melanoma, prostate, colon, brain and myeloid leukemia." (PMID 26068979, 2015). "The mRNA coding for GLI2, one of the most important downstream effectors of Hh signaling, was markedly upregulated (7.59-fold increase) in melanoma cells, whereas two key Hh repressors, PTCH1 and SUFU, were significantly reduced (0.341 and 0.458-fold decrease, respectively) compared to controls." (PMID 41596411, 2026). "We have discovered that Ptch1 is a multidrug transporter that contributes to the efflux of chemotherapeutic agents and plays an important role in the resistance to chemotherapy in adrenocortical carcinoma and melanoma cells." (PMID 35631574, 2022). "Accordingly, we observed that Ptch1 is endogenously expressed in various melanoma cell lines carrying or not a BRAF mutation." (PMID 33810240, 2021). "To investigate whether the HH-GLI pathway modulates ERK5 expression, we activated the HH-GLI pathway in a number of melanoma cell lines by silencing its negative regulator PTCH1 using lentiviral vectors expressing a specific shRNA (shPTCH1)." (PMID 34681917, 2021). "We showed that this compound strongly inhibited the resistance of Ptch1-overexpressing yeast to doxorubicin (dxr), a chemotherapeutic agent used to treat many cancers, as well as increased the cytotoxic effect of dxr in melanoma cells and strongly inhibited in vitro dxr efflux." (PMID 32526884, 2020). "Ptch1 is endogenously expressed in various melanoma cell lines, and we found that decreased Ptch1 expression strongly inhibited the efflux of doxorubicin, indicating that Ptch1 is involved in doxorubicin efflux in melanoma cells with or without the BRAF mutation." (PMID 32526884, 2020). "Our results suggest that the use of this inhibitor of Ptch1 drug efflux in combination with vemurafenib could be a promising therapeutic option to improve vemurafenib efficacy against resistant BRAFV600E melanomas." (PMID 32526884, 2020). "This makes Ptch1 a particularly attractive therapeutic target for cancers expressing Ptch1, such as lung, breast, prostate, ovary, colon, brain, adrenocortical carcinoma, and melanoma." (PMID 30110910, 2018). "Moreover, our recent studies showed that Ptch1 is present in primary tumor samples from all adrenocortical carcinoma patients of the cohort studied, and that Ptch1 is present in the metastases of all 365 melanoma patients of a TCGA cohort and correlates with a poorer the prognosis." (PMID 35631574, 2022). "We previously found that decreased Ptch1 expression in MeWo and A375 melanoma cells using silencing RNA against Ptch1 strongly inhibited the efflux of doxorubicin, indicating that Ptch1 is involved in doxorubicin efflux in melanoma cells carrying or not the BRAF mutation." (PMID 33810240, 2021). "However, we recently discovered that the Hedgehog receptor Ptch1, which is overexpressed in many cancers, also pumps chemotherapeutic agents such as doxorubicin out of cancer cell lines that were derived from melanoma and adrenocortical carcinoma (ACC), thereby conferring resistance to chemotherapy." (PMID 32526884, 2020). "Interestingly, we observed that the presence of the BRAFV600E inhibitor, vemurafenib, strongly inhibited the accumulation of doxorubicin in melanoma cells, and in silico docking studies suggested that doxorubicin and vemurafenib bind to Ptch1 at the cholesterol binding site." (PMID 32526884, 2020). "Contrarily, a previous study reported abnormally elevated PTCH1 levels in WM278, WM3248, A375, and SKMel94 melanoma cell lines." (PMID 41596411, 2026). "We observed reduced PTCH1 and SUFU repressors expression and GLI2 upregulation as common melanoma features." (PMID 41596411, 2026).
melanoma (continued). "Gene expression profiling revealed downregulation of two repressors, PTCH1 and SUFU, along with upregulation of the downstream effector GLI2 in melanoma cells compared to normal melanocytes." (PMID 41596411, 2026). "Separated analysis of primary and metastatic samples revealed significantly lower expression of PTCH1 and SUFU in advanced melanoma, confirming the relevance of the Hh signaling pathway in melanoma progression." (PMID 41596411, 2026). "In support of this increase, the analysis of GLI target genes over time (24 and 48 h) showed that MEK5DD induced the expression of PTCH1 and HIP1 mRNA already at 24 h in melanoma cells." (PMID 39998753, 2025). "In order to confirm HH-GLI pathway activation in melanoma cell lines, we analyzed relative gene and protein expression levels of the pathway components (GLI1, GLI2, GLI3, and PTCH1) on a panel of 14 human melanoma cell lines with different genetic backgrounds." (PMID 36139698, 2022). "To gain further insight into the neoplastic potential of skin nevi, we evaluated the expression of oncogenic markers characteristic of BCC (Ptch-1, Gli-1, and Gli-2), SCC (K8, K17, and p63), and melanoma (c-kit, MAGE, and CDK4)." (PMID 33509032, 2021). "Studies revealed that over 40% of the melanoma cell lines examined harbored significantly elevated levels of the hedgehog pathway mediators SMO, GLI2, and PTCH1 compared to melanocytes (p < 0.05)." (PMID 24287465, 2013). "Notably, cells derived from advanced metastatic lesions exhibited a more pronounced phenotype, characterized by significantly lower levels of three key repressor proteins, PTCH1, SUFU, and GLI3, compared to primary melanoma cells." (PMID 41596411, 2026). "This variant is currently classified as benign/likely benign, and it should be noted that it did not segregate with melanoma in family C11, since the brother of C11‐01 (C11‐03) was found to be PTCH1 wild‐type while being diagnosed with melanoma." (PMID 40072281, 2025). "Q-PCR analysis showed that the expression of two GLI target genes, PTCH1 and HIP1, is significantly reduced by ERK5 silencing, suggesting that ERK5 regulates not only the expression but also GLI transcriptional activity in melanoma cells." (PMID 39998753, 2025). "Indeed, our results demonstrate that the binding of methiothepin to Ptch1 increases the cytotoxicity of five different chemotherapeutic drugs (doxorubicin, cisplatin, oxaliplatin, vemurafenib and trametinib) against various melanoma cell lines carrying or not a BRAF mutation." (PMID 33810240, 2021). "In good agreement with our previous analysis performed on data from cutaneous melanoma tumors from patients, we observed a strong expression of Ptch1 in all the melanoma cell lines and the patients cells studied, while melanocytes do not express Ptch1." (PMID 33810240, 2021). "Given that sPAH inhibited the cholesterol efflux activity of Ptch1 on A375 cells in vitro, we wondered if this effect was not due to an increase of cholesterol in melanoma cells." (PMID 32526884, 2020). "Effects of iRF on melanoma cells (B16F10 cells) are, at least in part, correlated with inhibition of HH signaling, as evident by the decreased the expression of key players in HH pathway signaling such as GLI1 and PTCH-1 and the increase of SUFU expression." (PMID 23342114, 2013).
glioblastoma (19 papers, 2009 to 2024). The most malignant astrocytic tumor (WHO grade IV). "In this study, CCl4 rats had active Hh signaling as indicated by overexpression of Patched 1, Smoothened and Glioblastoma-2." (PMID 37923828, 2023). "Sustained HH signaling was found to be the consequence of lowered PTCH1 levels, regulated by microRNA, in glioblastoma multiforme." (PMID 35582031, 2021). "The transcriptomics data on 149 clinical cases of The Cancer Genome Atlas-Glioblastoma (GBM) database showed a robust correlation between PTCH1 and GLI1 mRNA expression as an indication of the canonical Shh pathway activity in this malignancy." (PMID 29558958, 2018). "Interestingly, the cell lines and samples showing PTCH1 promoter methylation were either glioblastomas (grade IV astrocytoma) or anaplastic astrocytomas (AIII)." (PMID 21059263, 2010). "In an animal model with glioblastoma, the treatment with LDE225 decreased the tumor size with downregulation of GLI1, GLI2, PTCH1, and SMO." (PMID 34642915, 2022). "In human primary glioblastoma initiating cells, sonidegib reduces levels of GLI1, GLI2, PTCH1, and PTCH2 messenger ribonucleic acid (RNA) and protein, as well as GLI1 and GLI2 translocation into the nucleus." (PMID 32973971, 2020). "Hh signaling appears to be active in glioblastoma multiforme (GBM)-derived neurospheres and glioma stem cell cultures (gliomaspheres), as they express GLI1, PTCH1, SMO and SHH." (PMID 26270676, 2015). "Binding of SHH-N to PTCH1 in the embryonic neural tube results in release of PTCH1-regulated inhibition of Smoothened (SMO) and regulation of the expression of SHH target-genes, like the glioblastoma (Gli) protein family members, Gli1, Gli2, and Gli3." (PMID 24865218, 2014). "For instance, the expression of PTCH1, the HH receptor, is significant higher in grade II/III gliomas and sonic hedgehog, one of the HH ligands, overexpresses in 80% of the human glioblastoma multiforme (GBM)." (PMID 28899410, 2017). "The transcriptomics data on 149 clinical cases of The Cancer Genome Atlas-Glioblastoma database showed a strong correlation between PTCH1 and GLI1 upregulated expression in GBM indicating that activation of the canonical SHH pathway might be associated with this malignancy." (PMID 36010607, 2022).
lung carcinoma (19 papers, 2012 to 2023). "The features of lung cancer associated with PTCH1 mutation remain to be investigated." (PMID 35982978, 2022). "One circulating tumor cell NGS assay in early-stage lung cancer patients showed that more than 50% of lung cancer patients presented four common mutations, including Notch1, EGFR, IGF2, and PTCH1." (PMID 36874015, 2023). "The positive correlation between NRF2 and PTCH1 expression was also confirmed in human lung cancer tissues." (PMID 32053600, 2020). "PTCH1 overexpression has been identified in a wide variety of cancers, including breast tumor, pancreatic neuroendocrine tumors, lung cancer, and gastric cancer." (PMID 31253779, 2019). "In this study, we applied WGCNA to explore the potential mechanisms of PTCH1-3’UTR-mediated-metastasis using TCGA lung cancer data, which included 517 NSCLC samples." (PMID 29435142, 2018). "In lung cancer cells, previous studies have reported a clear reduction in Ptch1 expression, main readout of Hedgehog activation, at 5 and 10 μM." (PMID 23667589, 2013). "The available data on lung cancer features associated with PTCH1 mutation are limited, and no previous study has focused on the long-term survival of these patients." (PMID 35982978, 2022). "For instance, in lung cancer, PTCH1-3ʹUTR promotes cell metastasis by absorbing miR-101-3p." (PMID 32066878, 2020). "The reduction of lung tumors after Smo inhibition in the transplantation model reported here is notable since these lung cancers did not have Ptch1 or Smo mutations." (PMID 22923130, 2012). "The levels of the Hh signaling components, SHH, PTCH1, and GLI1 were significantly reduced in CDO-depleted lung cancer cells compared with the scrambled control." (PMID 25369201, 2014). "We next analyzed the expression levels of canonical SHH signaling components—such as PTCH1, PTCH2, SMO, SUFU, and GLI1 proteins—in cultured human lung cancer cells (H1299, A549, HCC827, and H1975) and normal human lung fibroblasts (MRC-9 and WI38) by western blot analysis." (PMID 31783569, 2019). "Hence, NFIX with IL6ST, TIMP1, ITGB1, PTCH1, GGCX and NFAT5 genes may regulate the migration and invasion process and they could serve as potential therapeutic targets in patients with lung cancer to predict survival and improve prognosis." (PMID 28871224, 2017).